STAT3 (signal transducer and activator of transcription 3)
Diseases named in the same sentence as STAT3 in open-access papers (continued):
Sharing a sentence is not in itself a finding about the gene and the disease.
tumor (continued). "To achieve it, we analyzed STAT3 expression levels in the RCC tumor tissue and adjacent tumor tissue with the RCC data set (GSE40435), and the results demonstrated that STAT3 expression was significantly increased in RCC tumor tissue." (PMID 31838573, 2020). "Further, they revealed that the expression of MHC class II, CD80 and CD86 was increased in tumor-infiltrating DCs of STAT3-null mice." (PMID 32872659, 2020). "Of note, STAT3 hyper-activation has been found in tumor-infiltrating leukocytes, in which STAT3 orchestrates the crosstalk between cancer and immune cells." (PMID 32150944, 2020). "The results suggested that the mRNA transcriptional level of STAT3 was lower in tumors than normal tissues and mostly unrelated to tumor stage." (PMID 32486001, 2020). "According to our results, EVO can abrogate the activation of the c-Met/Src/STAT3 signaling axis and thus plays a role as a robust suppressor of tumor cell survival, proliferation, and angiogenesis." (PMID 32183146, 2020). "The present study explored how EHD extract regulated STAT3 and downstream target genes to inhibit tumour growth." (PMID 32382281, 2020). "STAT3 activation, IDO1 upregulation, and MDSC infiltration contribute to tumour-associated immune tolerance." (PMID 31819179, 2020). "What’s more, certain factors released by CAFs can modulate STAT3 signaling in other cell types in the tumor milieu." (PMID 32972405, 2020). "Noticeably, FAK inhibitor treatment led to a lower level of phosphorylated-STAT3 in murine PDAC tumor cells." (PMID 32664564, 2020). "IL-6 stimulation of JAK/STAT3 signaling can occur via an autocrine (cell response to its own secreted signal) or paracrine (signal secreted by other cells in the tumor microenvironment) manner, subsequently contributing to cellular growth and transformation." (PMID 33279931, 2020). "These suppression effects were enhanced when astaxanthin and si-STAT3 were combined, supporting the cell-based observation that astaxanthin exerts a significant inhibitory effect on tumor growth." (PMID 32784629, 2020). "In adaptive immune subsets, elevated STAT3 activity has the ability to inhibit the accumulation of effector T cells, thereby restraining their anti-tumor effects." (PMID 32972405, 2020). "STAT3 mediates tumor proliferation, invasion, anti-apoptosis, and stemness and acts as a therapeutic target." (PMID 33023006, 2020). "It was revealed that anti-tumor agents are able to suppress STAT3, resulting in a decrease in the proliferation and invasion of GC cells." (PMID 32545648, 2020). "The significant levels of tyrosine-phosphorylated STAT3 resulted in cancer cell apoptosis, resulting in lower tumor growth." (PMID 32545187, 2020). "Conversely, knocking down HP1α or STAT3 by stably expressing RNAi constructs HP1α-sh or STAT3-sh resulted in larger tumor volumes." (PMID 32087696, 2020). "In a preclinical NSCLC in vivo model, AZD4205 treatment inhibited tumor growth and STAT3 activation; these findings were more significant when AZD4205 was administered in combination with the EGFR inhibitor osimertinib." (PMID 33521321, 2020). "Due to the poor efficacy and high toxicity of STAT inhibitors in early pre-clinical trials, much research has focused on targeting upstream pathways to reduce phosphorylation and/or activation of STAT3 in tumour cells." (PMID 32899142, 2020). "Correspondingly, lower expression of p-STAT3 were observed in LTsc1KO mice at 6 months, and LTsc1KO mice exhibited lower expression of p-STAT3 in tumor compared to non-tumor tissue." (PMID 32363190, 2020). "And STAT3 tightly mediates diverse processes influencing tumor progression, including proliferation, apoptosis, angiogenesis, and immune response." (PMID 32486001, 2020). "In ApcMin/+ mice, three weeks treatment with 25 mg/kg quercetin (oral gavage), after tumor development, reduced muscle atrophy by lowering plasma IL-6 and muscle STAT3 activation." (PMID 33255345, 2020).
tumor (continued). "It is composed of NF-kB/Stat3/pan-kinase inhibitor curcumin and doxorubicin for enhanced tumor penetration." (PMID 32784356, 2020). "In this case, the chemokines have led to STAT3 activation in the tumor cells, which then has driven forward stemness and EMT." (PMID 33585241, 2020). "STAT3 also plays a pivotal role in driving tumor-promoting inflammation and evasion of anti-tumor immunity." (PMID 32365499, 2020). "S1PR1 is a G protein‐coupled receptor of lysophosphatidyl 1‐sphingosine, and its expression is increased in STAT3+ tumour cells." (PMID 31957271, 2020). "The restrain of tumor progression by STAT3 inhibition was correlated with an M1 macrophages and accumulation of NK cells." (PMID 32483429, 2020). "Circ-STAT3 facilitates cell proliferation, invasion, migration, stemness and tumor growth in HB via up-regulation of STAT3 and Gli2, indicating circ-STAT3 as a putative biomarker for HB." (PMID 32493490, 2020). "This leads to autocrine JAK-dependent STAT3 activation via gp130 engagement, thereby promoting tumor cell survival." (PMID 32365499, 2020). "Activated STAT3 protein acts as a transcriptional factor to regulate cell proliferation, apoptosis, angiogenesis, tumor invasion and metastasis." (PMID 31928530, 2020). "IL-17C-induced VEGF production was found to be closely related to STAT3 signaling pathway that promotes tumor growth." (PMID 32492770, 2020). "Univariate analysis of overall survival time showed that high p-STAT3 expression in tumor tissue, advanced TNM staging, intrahepatic metastases, PVTT and TACE times were the poor prognostic factors." (PMID 31942180, 2020). "Anti-tumor compounds suppress the STAT3 signaling pathway to restrict the proliferation and malignant behavior of GC cells." (PMID 32545648, 2020). "The capability of the formulation to inhibit NFkB and STAT3 activity can overcome the mechanisms of multidrug resistance in tumor cell mechanisms, making it effective in chemoresistant tumor cells." (PMID 32784356, 2020). "Once activated, STAT3 is translocated from cytosol into the nucleus where it induces transcription of various downstream target genes important for tumor induction and progression 28-31." (PMID 32328177, 2020). "Collectively, these results show that CD44 and STAT3 can regulate each other’s expression and cooperate across different tumor types to drive cancer invasion, metastasis, disease recurrence, and chemoresistance." (PMID 33335857, 2020). "Dual blockade of APE/Ref-1 and STAT3 promotes marked tumor cell apoptosis, which results in significant inhibition of migration." (PMID 33003453, 2020). "STAT3 (Signal transducer and activator of transcription 3), a critical transcriptional factor of tumorigenesis and a point of convergence of most activated oncogenic pathways, plays a pivotal role in tumor initiation and development." (PMID 32576206, 2020). "An increasing body of research evidence has clearly established the functional role of constitutive STAT3 activation in tumor induction, progression and drug resistance in multiple human cancers including NSCLC 1,2,9,10." (PMID 32328177, 2020). "In vivo, UTMC with STAT3-MB had strong anti-tumor effects, with significantly less tumor burden and greater survival compared to that of UTMC with microbubbles loaded with a mutant control decoy and untreated control groups (p<0.05)." (PMID 33206698, 2020). "Aberrant Stat3 activation stimulates tumor cell proliferation through inhibition of apoptosis, a function mediated by upregulation of the antiapoptotic gene Bcl-2." (PMID 32258099, 2020). "The process was mediated by STAT3 and mTOR activation, leading to tumor cell resistance against CD8+ T cell-mediated killing." (PMID 32582148, 2020). "In cholangiocarcinoma, a high expression of the oncoprotein, gankirin, promotes tumor proliferation, invasion and metastasis through the activation of the IL-6/STAT3 signaling pathway." (PMID 32283655, 2020).
tumor (continued). "Next to analysis of patient cohorts, experimental studies in other cancers corroborated STAT3‘s role as a tumor suppressor." (PMID 32365499, 2020). "Co-treatment of HeLa cells xenografts with piperine and Mitomycin C impaired tumor growth, decreased p-STAT3 and NF-κB and increased the apoptotic factors Bax, Bid, Caspases and PARP expression." (PMID 32669593, 2020). "Chronic inflammation activates the transcription factors such as NF-κB and signal transducer and activator of transcription 3 (STATA3) of tumor cells." (PMID 32051482, 2020). "Stat3 is closely related to the tumor initiation and development especially in ESCC, which is associated with persistent inflammation." (PMID 32258099, 2020). "STAT3 decoy-treated tumors showed markedly less Ki-67 staining compared to other groups, indicating greater inhibition of tumor cell proliferation." (PMID 33206698, 2020). "Numerous studies report how Shp1-mediated STAT3-downregulation represents a promising anti-cancer strategy to inhibit tumor growth and induce apoptosis in cancer cells." (PMID 32596156, 2020). "STAT3 inhibitors have shown anti-tumour activity in pre-clinical stages and have been successfully tested in phase-I clinical trials for safety and efficacy in solid tumours." (PMID 32046095, 2020). "Further, STAT3 is overexpressed in NSCLC tumour samples, and sorafenib can inhibit STAT3 activation to produce anticancer effects in NSCLC." (PMID 33448640, 2020). "Whereas Ptenpc−/− mice show slow, localized tumor progression, the additional deletion of Stat3 leads to rapid tumor growth, dissemination, and early death." (PMID 32323921, 2020). "The STAT-3 signaling pathway plays a prominent role in diverse cellular behaviors mediated by IL-6, including tumor cell survival, invasion, and metastasis." (PMID 32855767, 2020). "These genes are downstream targets of the STAT3 signaling pathway and can promote cell proliferation, inhibit apoptosis, and promote tumor development and progression." (PMID 33746736, 2020). "Another study demonstrated that tumor-derived factors prevented immature myeloid cells from differentiating into mature DCs via STAT3 activation." (PMID 32872659, 2020). "STAT3 plays a key role in the regulation of oncogenesis, cell survival, proliferation, angiogenesis, and tumor immunosuppression-related transcription." (PMID 33082817, 2020). "Mann-Whitney U test also demonstrated that the expression of p-STAT3 in tumor samples was significantly higher than one in adjacent liver samples." (PMID 31942180, 2020). "While phosphorylated-STAT3 expression per cell was high, it had a discrete expression pattern relatively well distributed throughout the tumor and spleen tissue." (PMID 33330068, 2020). "AZD1480, a JAK1/2 inhibitor, exhibited antitumor activity by inhibiting the growth of ES cells and tumor formation in xenograft models via the suppression of the IL-6/JAK2/STAT3 signaling pathway." (PMID 32754598, 2020). "Mechanistic investigations suggested that these inhibitory effects of Rg3 on MDSCs and corresponding cancer progression depend upon suppression of the STAT3-dependent pathway, tumor-derived cytokines, and the NOTCH signaling pathway." (PMID 33091036, 2020). "Consistent with the in vitro results, immunohistological analysis revealed that AT-I downregulated the expression of HK2, p-JAK2 and p-STAT3 in tumor tissuses of the xenograft mice." (PMID 32273843, 2020). "Although STAT3 activation is long-term and lasts for months, it highly increases the chance of getting a tumour as a result of chronic inflammation." (PMID 32863742, 2020). "STAT3 hyperactivation in tumor stroma is immunosuppressive and can increase the expression of certain cytokines and growth factors." (PMID 32972405, 2020). "Advanced studies have shown that STAT3 plays a vital role in restricting apoptotic cell death and promoting cell proliferation during tumor development." (PMID 32150979, 2020).
tumor (continued). "Importantly, it has been shown that the transcription factor STAT3 (a Proneural/Mesenchymal signature TF inferred by inTRINSiC) and its associated signaling network play key roles in promoting an immunosuppressive tumor microenvironment that may hinder immunotherapy." (PMID 32974985, 2020). "Importantly, also Stat6-deficient tumor epithelia were characterized by increased Stat3 phosphorylation suggesting that enhanced gp130-dependent Stat3 activation triggered by IL-6 and IL-11 could account for the pro-proliferative, pro-tumorigenic phenotype of Stat6−/− mice (data not shown)." (PMID 30353167, 2019). "Its combination with oxaliplatin attenuated DLD-1 xenograft tumor burden and reduced p-STAT3 in vivo." (PMID 30736824, 2019). "The same observation holds true in the Cox proportional hazards regression (HR) model in univariate and then in multivariate analyses, including p-Stat3 Y705 expression status (> 20%) even after adjusting for age and different tumour localization." (PMID 31690341, 2019). "It has been shown that STAT3 is required for the formation of tumor spheres and the viability of the cancer stem cell pool in many different tumors." (PMID 31557897, 2019). "The western blot assay and immunohistochemistry studies showed that the expression of MMP9, MMP2, VEGF and STAT3 in tumor and liver tissues were significantly decreased in a dose-dependent manner." (PMID 30651572, 2019). "Phosphorylation of STAT3 through various mechanisms leads to the transcription of several genes involved in cell transformation, expansion, and regulation of the tumor microenvironment." (PMID 31684088, 2019). "Our laboratory previously demonstrated that 2 weeks of systemic IL-6 overexpression is sufficient to induce STAT3 and suppress basal muscle protein synthesis in non-tumor-bearing mice." (PMID 30918582, 2019). "Results showed that ZBTB28 inhibited NANOG, BMI1, OCT4, KLF4, TIP30 and STAT3 mRNA expression in tumor cells." (PMID 31754389, 2019). "Our data show that HFD feeding increases tumor size, STAT3 phosphorylation, and palmitic acid (PA) level in the xenograft tissues of the PCa-bearing xenograft mouse model." (PMID 31474764, 2019). "It is indeed able to inhibit multiple oncogenic pathways such as STAT3, is constitutively activated in tumor cells, and can potentiate the immune response." (PMID 31547402, 2019). "The same team proposed that corosolic acid and oleanic acid can prevent tumor formation through their capacity to suppress macrophages M2 polarization and tumor cell proliferation by inhibiting STAT3 activation." (PMID 31480382, 2019). "Several signaling pathways, including STAT3 are known to regulate the expression of various genes involved in the process of tumor migration and invasion." (PMID 31456939, 2019). "It has been demonstrated that STAT3-siRNA-loaded NPs have high cellular uptake by tumor cells leading to their high efficacy in reducing the malignancy of cancer cells." (PMID 31569687, 2019). "Stat1 is known for its anti-tumor activity, whereas Stat3 is known for promoting tumor progression and immunosuppression." (PMID 31709183, 2019). "To address the physiological relevance of this finding, we treated RCC cells in vitro with IL-6, a tumor microenvironment known to activate STAT3." (PMID 30796200, 2019). "Collectively, these results indicate that ajoene extract alleviates muscle atrophy by modulating JAK/STAT3 and SMADs/FoxO signaling pathways in tumor-bearing mice." (PMID 31717643, 2019). "It is assumed that the production of proinflammatory cytokines, which activate transcription factors, such as NF-κB and STAT3 in pre-malignant cells, is the main tumor initiating mechanism." (PMID 30862050, 2019). "Targeting STAT3 signaling therefore represents an attractive strategy to increase CTL responses in the tumor-bearing host." (PMID 31480382, 2019).
tumor (continued). "The tumor-suppressive role of STAT3 is attributed to its ability to inhibit NF-κΒ-induced transcription of the proangiogenic chemokine Cxcl1, thereby suppressing tumor vascularization and tumor progression." (PMID 30931929, 2019). "We then analyzed microRNA (miRNA) transcriptional targets of STAT327, and observed increased miR-21 and miR-181b in tumor samples carrying mutations in PTPRT or JAK2, while non STAT3 targets, such as miR-126, were similar." (PMID 31844068, 2019). "It appears that curcumin- and STAT3 siRNA-loaded liposomes significantly down-regulate the expression of STAT3 protein leading to the inhibition of tumor invasion and a remarkable reduction in tumor weight and tumor volume." (PMID 31569687, 2019). "Several recent studies have shown that STAT3 transcriptionally regulates key tumor-driving genes that are essential for tumor pathogenesis, such as TNFRSF1A, MCY and SOX1." (PMID 31747963, 2019). "It was shown that the treatment of ECN decreased tumor sizes and tumor weights compared with the control group and ECN inhibited STAT3 activation in tumor tissues." (PMID 31337063, 2019). "In this study, it was demonstrated that Stat3 gene silencing in 4T1 mouse cell line not only led to tumor growth restriction but also altered the immunologic profile in vivo." (PMID 31581535, 2019). "STAT3, as an important transcript factor, is also required for the suppressive function of tumor MDSCs 2, 38-40." (PMID 31413755, 2019). "A recent study on tumor cells revealed that lysosomal V-ATPase activity is enhanced by the cytosolic transcription factor signal transducer and activator of transcription-3 (STAT-3)." (PMID 31555270, 2019). "Essentially, higher-grade tumors showed a significant reduction in STAT3 expression when compared to their low-grade tumor counterparts." (PMID 32039025, 2019). "When FBS was used for the activation of starved tumor cells, we found that STAT3 phosphorylation was enhanced in the MVP knockdown LLC cells in both basal level group and FBS stimulated group." (PMID 31092229, 2019). "We found a significant reduction of tumor growth in pre-treated and post-treated JAK inhibited slices, as well as a reduced number of activated astrocytes marked by STAT3 phosphorylation within the tumor margin." (PMID 31186414, 2019). "We also observed different requirements for STAT3 in the primary tumor and at metastatic sites, E-STAT3 being more dominant in pancreatic lesions and T-STAT3 seeming to be more important at metastatic lesion." (PMID 31796877, 2019). "Silencing or inhibition of STAT3 or STAT5 signaling impairs tumor growth and survival in murine and human studies, while only slightly affecting normal differentiated cells." (PMID 31861073, 2019). "In mice injected subcutaneously with an NPM-ALK positive tumor cell line, treatment with an anti-sense oligonucleotide specific for STAT3 led to increased involution and necrosis of tumors and decreased tumor burden." (PMID 31684088, 2019). "In the xenograft mouse models, the HFD-increased tumor growth and STAT3 phosphorylation in tumors are reversed by STAT3 inhibition." (PMID 31474764, 2019). "In summary, we demonstrate for the first time that PTC-209 inhibits STAT3 signaling pathway, leading to the inhibition of cellular proliferation and the induction of cellular death, consequently decreasing tumor growth." (PMID 31695609, 2019). "CD163-targeted crosolic acid-containing liposomes prevent the expression of STAT3 in macrophages, resulting in enhanced anti-tumor immunity by increasing TNF-α, IFN-γ, IL-12 and IL-2 levels, and decreasing the IL-10 level." (PMID 31569687, 2019). "Mechanistically, SMYD2 physically interacts with STAT3 and NF-κB p65 and increases their methylation and phosphorylation, promoting tumor growth and metastasis." (PMID 31088482, 2019).